MAP3K1 (mitogen-activated protein kinase kinase kinase 1)
Diseases named in the same sentence as MAP3K1 in open-access papers (continued):
Sharing a sentence is not in itself a finding about the gene and the disease.
heart failure (2 papers, 2022 to 2025). Inability of the heart to pump blood at an adequate rate to meet tissue metabolic requirements. "However, the role of MAP3K1 remains controversial, as heart failure and sudden death was reported in MAP3K1-null mice under pressure overload." (PMID 41015772, 2025). "Notably, MAP3K1 knockout mice develop comparable hypertrophy but worse heart failure after pressure overload, implying its primary protective role may also involve preventing maladaptive remodeling." (PMID 41015772, 2025).
hepatocellular carcinoma (2 papers, 2020 to 2024). A malignant tumor that arises from hepatocytes. "In AEG-1-C75S liver, activation of cell proliferation and invasion were detected which were associated with activation of oncogenic MAP2K4, MAP3K1, TGFA, NRF2, and STAT3 signaling ultimately contributing to hepatocellular carcinoma." (PMID 38677511, 2024).
hydatidiform mole (2 papers, 2021 to 2022). A gestational trophoblastic disorder characterized by marked enlargement of the chorionic villi, hyperplasia of the villous trophoblastic cells and hydropic changes. "Further study at our laboratory showed that another miRNA, miR-196b, inhibits cell migration and invasion through targeting MAP3K1 (encoding mitogen-activated protein kinase kinase kinase 1) in hydatidiform moles." (PMID 35246136, 2022).
Hyperglycemia (2 papers, 2016 to 2023). An increased concentration of glucose in the blood. "Therefore, MAP3K1 is a member of MAPK signal transduction in response to stress stimuli of hyperglycemia, and genomic variation at this gene may have important roles in beta cell death and insulin resistance and inflammatory cytokine secretion." (PMID 27942499, 2016). "MAP3K1 activates the ERK and JNK kinase cascade in response to various stress stimuli (i.e., cytokines, free fatty acids and hyperglycemia), and appears a crucial mediator in the transition from obesity to T2D." (PMID 37510186, 2023).
lobular carcinoma (2 papers, 2020 to 2021).
lupus (2 papers, 2016 to 2023). "In addition, the gene expression of sh2d1a, map3k1, spn and stat5b was enhanced after NaCl treatment, consistent with the findings in lupus CD4+T cells." (PMID 27325182, 2016). "In our study, we found that MSCs regulate circulating miR-320b and miR-320b/MAP3K1 expression to restrain CD4+ T-cell proliferation in SLE and lupus mice." (PMID 37928434, 2023).
lymphoma (2 papers, 2011 to 2013). A malignant (clonal) proliferation of B- lymphocytes or T- lymphocytes which involves the lymph nodes, bone marrow and/or extranodal sites. "Median expression levels were invariably higher for AURKB, BCAT1, BIRC5, BUB1B, PBK and RACGAP1 and lower for FOSB, MAP3K1 and RIN3 by qPCR in lymphoma versus normal B cell samples in both species." (PMID 24130802, 2013).
neuroendocrine carcinoma (2 papers, 2024 to 2026). A malignant neuroendocrine neoplasm composed of cells containing secretory granules that stain positive for NSE and chromogranin.
squamous carcinoma (2 papers, 2022 to 2024). "Thus, our studies in squamous carcinoma propose that genomic imbalances related to the EGFR and MAP3K1 may be an important factor in resistance to PDT." (PMID 39766391, 2024).
type 2 diabetes (2 papers, 2013 to 2016). "The seven loci shed new light on regions containing genes with a reported role for type 2 diabetes (PPARG, ADAMTS9, VEGFA), lipids (GRB14, MAP3K1) and hormone metabolism (HSD17B4)." (PMID 23754948, 2013).
Alzheimer disease (1 paper, 2022). A progressive, neurodegenerative disease characterized by loss of function and death of nerve cells in several areas of the brain leading to loss of cognitive function such as memory and language. "These include APOE, PRKAA1, and MAP3K1, which were previously reported to be associated with Alzheimer’s disease (AD)." (PMID 35580864, 2022).
autoimmune disease (1 paper, 2023). A disorder resulting from loss of function or tissue destruction of an organ or multiple organs, arising from humoral or cellular immune responses of the individual to their own tissue constituents. "ANKRD55 encodes ankyrin repeat domain-containing protein 55, which mediates protein–protein interactions and may have a role in autoimmune diseases, whereas MAP3K1, which is also known as MEK kinase 1, is a serine/threonine kinase that belongs to the mitogen-activated protein kinases (MAP3K) family." (PMID 36980976, 2023).
bone sarcoma (1 paper, 2023). A sarcoma that arises from the bone.
bone tumors (1 paper, 2023). "In bone tumors, the MSKCC cohort had significantly fewer mutations in MAP3K1, CREBBP, MCL1, GNAQ, MEF2B, MYCN, SDHA, and SMARCA4." (PMID 37546405, 2023).
cervical squamous cell carcinoma (1 paper, 2020). A squamous cell carcinoma arising from the cervical epithelium. "In the COSMIC database, the same FBXW7 mutation was found in cervical squamous cell carcinoma and endometrioid carcinoma, and the same MAP3K1 mutation was found in cutaneous squamous cell carcinoma." (PMID 32429412, 2020).
COVID-19 (1 paper, 2023). A disease caused by infection with severe acute respiratory syndrome coronavirus 2. "We also observed COVID-19-specific enrichment of signaling genes such as MAP3K1, which helps activate JNK and ERK pathways, and STAT6, which is involved in IL-4 and IL-13 signaling." (PMID 36992700, 2023).
dental fluorosis (1 paper, 2024). A condition that results from excessive fluoride ingestion during tooth development, resulting in tooth discoloration ranging from white streaks to brown stains and cracks or pits in the tooth enamel. "Furthermore, the effect of miR-1a-3p and its target gene Map3k1 on dental fluorosis needs to be further verified in animal experiments." (PMID 37782397, 2024).
ductal carcinoma (1 paper, 2019). "While the association between mast cell gene expression and CDH1 mutation was as expected linked to lobular breast cancer, PIK3CA and MAP3K1 mutations were selectively associated with mast cell gene expression when considering only ductal carcinoma." (PMID 30993001, 2019).
glaucoma (1 paper, 2023). Increased pressure in the eyeball due to obstruction of the outflow of aqueous humor. "However, the possible relevance of ANKRD55 and MAP3K1 in glaucoma is unknown." (PMID 36980976, 2023).
gonadal agenesis (1 paper, 2024). A congenital disorder characterized by the complete absence of gonadal tissue. "Among the known genes associated with nonsyndromic 46, XY gonadal agenesis, variants of SRY, NR5A1, and MAP3K1 are the most common." (PMID 38915825, 2024).
hepatitis B (1 paper, 2021). "It has also been shown that miR-125b is associated with hepatitis B and has been targeted with genes that include IL6, DDX3X, STAT2, STAT3, SMAD4, CDKN1B, MAP3K1 and so on from our results." (PMID 34988221, 2021).
Hypergonadotropic hypogonadism (1 paper, 2020). Reduced function of the gonads (testes in males or ovaries in females) associated with excess pituitary gonadotropin secretion and resulting in delayed sexual development and growth delay. "While patient 2 exhibited hypergonadotropic hypogonadism similar to that of previously reported patients with pathogenic MAP3K1 variants, patient 1 manifested undermasculinized external genitalia in combination with normal blood levels of gonadotropins and AMH." (PMID 33060765, 2020).
lentivirus infection (1 paper, 2024). Virus diseases caused by the Lentivirus genus. "The expression of MAP3K1 in GBM patients‐derived organoids was knockdown by lentivirus infection." (PMID 39443331, 2024).
lymph node metastasis (1 paper, 2014). "The associations between MAP3K1 rs889312 genotypes and survival of individuals with diffuse-type gastric cancer were further assessed by stratified analysis based on tumor location, differentiation, tumor size, depth of invasion, lymph node metastasis, distant metastasis, and TNM stage." (PMID 24759887, 2014).
osteoporosis (1 paper, 2025). A condition of reduced bone mass, with decreased cortical thickness and a decrease in the number and size of the trabeculae of cancellous bone (but normal chemical composition), resulting in increased fracture incidence. "The LASSO regression algorithm established an osteoporosis-related model, identifying six disease-related candidate core target genes (IGF1R, NR3C1, MAP3K1, BRAF, WNK4, CNR2)." (PMID 40692598, 2025).
pancreatic adenocarcinoma (1 paper, 2024). "RNA sequencing data showed overexpression of α2 integrin, β1 integrin, and MAP3K1 in pancreatic adenocarcinomas compared to normal pancreas." (PMID 39666682, 2024).
papilloma (1 paper, 2023). A benign epithelial neoplasm that projects above the surrounding epithelial surface and consists of villous or arborescent outgrowths of fibrovascular stroma. "The result showed that papilloma carried higher mutation rate of genes, such as MPRIP, HRAS, and MAP3K1, while PUC carried a higher mutation rate of genes, such as FGFR3 and PPFIBP1 (Fisher’s exact test, p < 0.05)." (PMID 37704624, 2023). "We further found that higher expression of HRAS was positively correlated with higher phosphorylation of MAP3K1, MAPK1, and RPS6KA3, and the expression of RPS6KA3 was higher in papilloma than PUC." (PMID 37704624, 2023).
pulpitis (1 paper, 2021). Inflammation of the dental pulp. "Since these pathways mentioned here have been verified to be implicated in pulpitis, MAP3K1 can be speculated to be also involved in pulpal inflammation." (PMID 33777260, 2021).
Sepsis (1 paper, 2025). Sepsis is defined as life-threatening organ dysfunction caused by a dysregulated host response to infection. "Notably, upregulation of ADCK1, IGF1R, and MAP3K1 at the transcriptional level was found to predict higher sepsis risk, while increased expression of BLK and KCNJ15 correlated with lower risk." (PMID 40761792, 2025). "Likewise, serine/threonine kinases MAP2K5 and MAP3K1, both classified as Tier 1 targets, are integral components of the MAPK signaling cascade, orchestrating oxidative stress responses, inflammatory mediator release, and apoptosis during sepsis." (PMID 40761792, 2025).
T-cell lymphoma (1 paper, 2021). "For T-cell lymphoma six genes are found in cosmic (JAK1, PLCG1, FYN, ARID1A, EP300, and MAP3K1), and 13 are known oncogenes." (PMID 34570764, 2021).
teratoma (1 paper, 2025). A non-seminomatous germ cell tumor characterized by the presence of various tissues which correspond to the different germinal layers (endoderm, mesoderm, and ectoderm). "Ectopic differentiated cells are also found within the incorrect organs after map3k1 RNAi, and ultimately teratomas form." (PMID 40093160, 2025). "We suggest that map3k1 acts within planarian progenitors to mediate such spatial restriction on differentiation, and that this is critical for preventing mistargeting differentiation to the incorrect location or organ, and to prevent teratoma formation." (PMID 40093160, 2025).
thyroid cancer (1 paper, 2025). "The downregulation of MAP3K1 in the ATC component was partially unexpected, since data in thyroid cancer show its role in promoting PTC formation." (PMID 40965626, 2025).
tubular carcinomas (1 paper, 2018). "Of the remaining tubular carcinomas, 3 fell in IntClust 7 (with 16q loss and MAP3K1 mutations), 4 fell in IntClust 8 (1q gain, 16q loss and PIK3CA and GATA3 mutations) and 6 belonged to IntClust 4 (few copy number alterations and activation of immune pathways)." (PMID 29532008, 2018).
tumor (105 papers, 2007 to 2026). "This is likely due to the contribution of tumor suppressors and oncogenes to cancer aneuploidies, such as the TERT oncogene, encoded on chromosome 5p, and tumor suppressors like MAP3K1, encoded on chromosome 5q." (PMID 39930267, 2025). "There was also an enrichment of PIK3CA and MAP3K1 mutations in mG1 samples, indicating the specificity of this mechanism in tumor development." (PMID 40740860, 2025). "On the other hand, “Tissue Invasion and Metastasis”, involving 18 genes such as MUC16, FGF4, and MAP3K1, remains one of the leading causes of mortality in BC patients, emphasizing the importance of these genes in the tumor’s ability to spread to other tissues." (PMID 40136626, 2025). "We identified newly emerging mutations in genes that were not covered by our targeted NGS panel such as ATM, NOTCH2, EP300, ARID1A and MAP3K1 and also noticed an increase in tumor mutational burden (TMB) in some cases during progression." (PMID 40973765, 2025). "Tumor cells with varying Map3k1 mutation status in the coculture system were transfected with siDdx17 and the actinomycin D treatment assay was performed again." (PMID 39531335, 2024). "Mechanistically, MAP3K1 mutation suppressed MHC-I–mediated tumor antigen presentation through promoting the degradation of antigen peptide transporter 1/2 (TAP1/2) mRNA, thereby driving tumor immune escape." (PMID 39531335, 2024). "We discovered that the immunosuppressive tumor microenvironment was associated with a high prevalence of MAP3K1 mutation, suggesting that MAP3K1 plays an important role in mediating resistance to immunotherapy." (PMID 39531335, 2024). "In ER+ tumours, mutations in both MAP3K1 (hazard ratio (HR)=0.56, CI=0.38–0.82) and GATA3 (HR=0.58, CI=0.4–0.82) were associated with longer survival." (PMID 27161491, 2016). "Similarly, in CRC, down-regulation of hsa-mir-200b-3p has been associated with increased expression of MAP3K1, promoting tumor progression and metastasis." (PMID 39901302, 2025). "MAP3K1 mutations can lead to alterations in tumor cell proliferation and survival." (PMID 39594781, 2024). "Map3k1 mutation could reshape the immune microenvironment by reducing the surface MHC-I expression to promote tumor growth." (PMID 39531335, 2024). "In our study, we reported for the first time that Map3k1 mutation could promote tumor growth through attenuating CD8+ T cell–mediated antitumor immunity by downregulating tumor antigen presentation." (PMID 39531335, 2024). "However, in our dataset, primarily composed of TNBC samples, we found a striking mutation pattern for MAP3K1, which was altered in all the samples except for one primary tumor (P15′)." (PMID 37761830, 2023). "This same tumor also had a low frequency frameshift mutation in MAP3K1 G394Kfs*28." (PMID 37369741, 2023). "In addition, mutations in MAP3K1 are associated with sensitivity to MEK inhibitors in multiple patient‐derived xenograft (PDX) tumor models." (PMID 34331411, 2021). "Loss of MAP3K1 expression reduces cell migration and invasion and delays tumor metastasis." (PMID 33863951, 2021). "In addition, copy number loss and somatic mutations of MAP3K1 were reported in a significant fraction of human tumor samples." (PMID 34404765, 2021).
tumor (continued). "With regard to the prognostic factors, the FGFR2 SNP rs1219648 was associated with tumor differentiation (p-value = 0.018), the MAP3K1 SNP rs889312 was linked to the HER2 marker (p-value = 0.04), and the IGF1 SNP rs2373721 was correlated with progesterone receptor status (p-value = 0.04)." (PMID 33112566, 2020). "However, the co-presence of alterations in MAP3K1, a putative tumor suppressor, with PIK3CA mutations was associated with a significant clinical benefit rate (CBR)." (PMID 31552290, 2019). "Our work aimed to characterize whether LoF mutations in MAP3K1 provide selective advantage for tumor progression and how this impacts on resistance to PI3K pathway targeted therapies." (PMID 29765551, 2018). "Therefore to further characterize the phenotypic impact of MAP3K1 depletion in tumor fate we implanted parental and MAP3K1-deficient MCF7 cells in nude mice and followed their growth for 28 days." (PMID 29765551, 2018). "In our cohort we found that patients carrying one or two minor alleles of rs889312 in MAP3K1 were less likely to have lymph-node-positive breast cancer, suggesting that the invasive potential of the tumour in these patients might be lower." (PMID 17997823, 2007). "Recent genomic and mechanistic studies have revealed MAP3K1's paradoxical, context-dependent roles as both an oncogene and a tumor suppressor." (PMID 41972694, 2026). "For instance, in CRC, increased expression of MAP3K1 has been correlated with poor prognosis and aggressive tumor behavior." (PMID 39901302, 2025). "In our cohort, MAP3K1 was consistently downregulated across all tumor subtypes, with the strongest suppression observed in TNBC." (PMID 41465262, 2025). "Downregulation of MAP3K1 coincided with a significant upregulation of miR-21-3p, a well-established oncomiR known to repress multiple tumor suppressor." (PMID 41465262, 2025). "To confirm the effect of Map3k1 on this pathway, we performed the in vitro coculture assay again and collected tumor cells to measure the surface expression of MHC-I and OVA antigen." (PMID 39531335, 2024). "To further confirm the necessity of CD8+ T cell–mediated tumor immunity in Map3k1-modulated tumor growth, we used a CD8 neutralizing antibody to deplete CD8+ T cells in mice." (PMID 39531335, 2024). "We observed that depletion of CD8+ T cells abolished the growth difference among tumors with varying Map3k1 mutation status, indicating the critical role of CD8+ T cells in mediating the effects of Map3k1 on tumor growth in vivo." (PMID 39531335, 2024). "Consistently, we observed comparable mRNA and protein levels of TAP1/2 between Map3k1-WT and Map3k1-mut tumor cells in the coculture system after silencing Ddx17." (PMID 39531335, 2024). "Whole brain HE staining showed that tumours in MAP3K1 knockdown group were smaller and more defined." (PMID 39443331, 2024). "The reduced cytotoxicity of CD8+ T cells in the coculture system induced by Map3k1-mut/mut’ tumor cells was confirmed by lactate dehydrogenase (LDH) assay." (PMID 39531335, 2024). "Map3k1-mut lost this effect, leading to promoted degradation of Tap1/2 mRNAs in Map3k1-mut compared to Map3k1-WT tumor cells." (PMID 39531335, 2024). "Signaling pathways involving AKT1 and MAP3K1 influence cell survival and apoptosis, enhancing tumor growth when activated." (PMID 39273340, 2024). "After TMZ injection, the tumour volume of MAP3K1 knockdown group was significantly reduced compared with the control group." (PMID 39443331, 2024). "Overall, these findings suggest that Map3k1-mut/mut’ tumor cells have an enhanced ability to evade killing by CD8+ T cells in vitro." (PMID 39531335, 2024). "While the exact impact of MAP3K1 mutations on survival in ILC remains less clearly defined, their presence is often correlated with specific tumor characteristics, including a lower grade and potentially better responses to endocrine therapy." (PMID 39594781, 2024).